PLPP1 (phospholipid phosphatase 1)
Description:
Magnesium-independent phospholipid phosphatase of the plasma membrane that catalyzes the dephosphorylation of a variety of glycerolipid and sphingolipid phosphate esters including phosphatidate/PA, lysophosphatidate/LPA, diacylglycerol pyrophosphate/DGPP, sphingosine 1-phosphate/S1P and ceramide 1-phosphate/C1P. Also acts on N-oleoyl ethanolamine phosphate/N-(9Z-octadecenoyl)-ethanolamine phosphate, a potential physiological compound. Through its extracellular phosphatase activity allows both the hydrolysis and the cellular uptake of these bioactive lipid mediators from the milieu, regulating signal transduction in different cellular processes. It is for instance essential for the extracellular hydrolysis of S1P and subsequent conversion into intracellular S1P. Involved in the regulation of inflammation, platelets activation, cell proliferation and migration among other processes. May also have an intracellular activity to regulate phospholipid-mediated signaling pathways (By similarity).
Synonyms: PAP-2a; LPP1; PPAP2A; LLP1a; PAP2
Tractability: Antibody: UniProt places it where antibodies can reach, with high confidence; its Gene Ontology location is reachable by antibodies, with high confidence; UniProt predicts a signal peptide or a membrane-spanning region; the Human Protein Atlas places it where antibodies can reach. PROTAC: ubiquitination databases record sites on it; its protein half-life has been measured.
Gene: Protein-coding gene on chromosome 5 (55,424,849 to 55,535,035, reverse strand). Ensembl gene ENSG00000067113.
Subcellular location: Cell membrane; Apical cell membrane; Membrane raft; Membrane, caveola
Subcellular location (Human Protein Atlas): Plasma membrane
Pathways (Reactome):
Metabolism: Sphingolipid catabolism
Gene Ontology:
Molecular function: ceramide-1-phosphate phosphatase activity; lipid phosphatase activity; phosphatidate phosphatase activity; protein binding; sphingosine-1-phosphate phosphatase activity; diacylglycerol diphosphate phosphatase activity; lysophosphatidic acid phosphatase activity
Biological process: ceramide metabolic process; phospholipid dephosphorylation; phospholipid metabolic process; signal transduction; sphingosine metabolic process; androgen receptor signaling pathway; negative regulation of cell population proliferation; nuclear receptor-mediated steroid hormone signaling pathway; phospholipase C-activating G protein-coupled receptor signaling pathway; regulation of lipid metabolic process; sphingolipid catabolic process
Cellular component: apical plasma membrane; extracellular exosome; membrane; membrane raft; plasma membrane; caveola
Genetic constraint (gnomAD): Loss-of-function variants: 24 observed, 31.54 expected, observed/expected ratio (o/e) 0.76, 90% interval 0.55 to 1.07. The upper end of that interval is the gene's LOEUF score, 1.07, which puts it in group 4 of 6, group 1 being the genes least tolerant of losing a copy. Missense variants: 318 observed, 347.56 expected, observed/expected ratio (o/e) 0.91, 90% interval 0.83 to 1. Synonymous variants: 143 observed, 127.99 expected, observed/expected ratio (o/e) 1.12, 90% interval 0.97 to 1.28.
Homologues: Orthologues: guinea pig PLPP1 (93% identical), chimpanzee PLPP1 (89% identical), macaque PLPP1 (88% identical), pig PLPP1 (86% identical), rabbit PLPP1 (85% identical), dog PLPP1 (84% identical), mouse Plpp1 (74% identical), rat Plpp1 (74% identical), zebrafish plpp1a (64% identical), zebrafish PLPP1 (62% identical), Drosophila melanogaster wun (40% identical), Caenorhabditis elegans plpp-1.1 (40% identical), and 7 more. Paralogues in human: PLPP2 (56% identical), PLPP3 (52% identical), PLPPR4 (30% identical), PLPPR1 (28% identical), PLPPR3 (27% identical), PLPPR5 (26% identical), PLPPR2 (24% identical), PLPP4 (22% identical), PLPP5 (22% identical).
Diseases named in the same sentence as PLPP1 in open-access papers:
PLPP1 is named in the same sentence as 24 diseases in open-access papers, as found by Europe PMC text mining. Sharing a sentence is not in itself a finding about the gene and the disease. The quoted sentences say what the papers report.
lung carcinoma (5 papers, 2017 to 2025). "Collectively, these results indicated that PLPP1 expression was low and associated with poor prognosis in lung cancer." (PMID 38069368, 2023). "Furthermore, we used the database of the Kaplan–Meier (KM) plotter to analyze the association between PLPP1 mRNA expression and the prognosis of lung cancer." (PMID 38069368, 2023). "In cisplatin-resistant lung cancer cells, downregulated expression of PLPP1 leads to the accumulation of PA and a reduction in DG." (PMID 40919194, 2025). "In lung cancer, the expression of phospholipid phosphatase 1 (PLPP1), which catalyzes the synthesis of phosphatidylcholine (PC) and phosphatidylethanolamine (PE), is reduced in CD8+ T cells within tumors." (PMID 40696413, 2025). "Z-ligustilide+cisplatin induced cell cycle arrest and promoted the cell apoptosis of cisplatin-resistant lung cancer cells by inhibiting PLPP1-mediated phospholipid synthesis." (PMID 38069368, 2023). "A more detailed analysis revealed that the overall survival of lung cancer patients with low PLPP1expression was shorter than patients with high PLPP1 expression in the chemotherapy group." (PMID 38069368, 2023). "In our study, the inhibition of p-AKT expression and a decrease in PIP3 levels occurred in cisplatin-resistant lung cancer treated with Z-ligustilide+cisplatin; however, the knockdown of PLPP1 reversed the effects." (PMID 38069368, 2023). "We discovered that PLPP1 was upregulated in cisplatin-resistant lung cancer cells with the treatment of Z-ligustilide+cisplatin compared with cisplatin-resistant lung cancer cells." (PMID 38069368, 2023). "We found that lung cancer patients with low PLPP1 expression had a shorter overall survival than patients with high PLPP1 expression during the 60-month follow-up." (PMID 38069368, 2023). "Interestingly, the expression of PLPP1 decreased in cisplatin-resistant lung cells compared with lung cancer cells, and the knockdown of PLPP1 increased the cell viability of cisplatin-resistant cells." (PMID 38069368, 2023). "The immunohistochemical staining of PLPP1 in 76 lung cancer tissue samples was further performed." (PMID 38069368, 2023). "In lung cancer, PD-1 signaling in intratumoral CD8+ T cells induced GATA1 binding to the promoter region of phospholipid phosphatase 1 (PLPP1), which inhibited the expression of PLPP1." (PMID 40432130, 2025). "Conversely, the expression levels of PLPP1, PLPP3 and PLPP7 were decreased to varying degrees compared with those in the ANT, indicating that different members of the PLPP family have oncogenic or tumor-suppressive roles in the development of lung carcinoma." (PMID 28851360, 2017).
breast carcinoma (4 papers, 2017 to 2023). "PLPP1 has been recognized as one of 12 genes linked with relapse-free survival in breast cancer patients." (PMID 32887262, 2020). "Amin and colleagues have shown that PLPP1, a downstream ErbB2 signaling target, may be used as a diagnostic marker in breast cancer." (PMID 28851360, 2017). "Specifically, the reduced expression levels of PLPP1 and PLPP3 had been observed in colon cancer and breast cancer." (PMID 37996944, 2023). "In this study, we explore the role of LPP mRNA expression (LPP1 gene name PLPP1 and historically PAPP2A; LPP2 gene name PLPP2, PAPP2C; LPP3 gene name PLPP3, PAPP2B) within the human breast cancer TME via in silico research approaches using three large independent cohorts." (PMID 37190226, 2023).
lung adenocarcinoma (2 papers, 2017 to 2023). A carcinoma that arises from the lung and is characterized by the presence of malignant glandular epithelial cells. "The Cancer Genome Atlas (TCGA) and Genotype-Tissue Expression (GTEx) data set analysis showed that PLPP1 had a lower expression in 483 lung adenocarcinoma (LUAD) and 486 lung squamous cell carcinoma (LUSC) than in corresponding normal tissues." (PMID 38069368, 2023).
acute myeloid leukemia (1 paper, 2021). Acute myeloid leukemia (AML) is a group of neoplasms arising from precursor cells committed to the myeloid cell-line differentiation. "PLPP1 was differentially elevated in lymphoid neoplasm diffuse large B-cell lymphoma (DLBC), acute myeloid leukemia (LAML), and thymoma (THYM)." (PMID 34917513, 2021).
breast tumors (1 paper, 2021). "However, the expression of PLPP1 and PLPP2 was decreased and increased, respectively, in primary breast tumors compared to normal breast tissue." (PMID 34235182, 2021).
diabetes (1 paper, 2017). "In the scenario that inhibition of PLPP1 is too risky for an anti-diabetes therapy, the information learned from this study can be used to investigate other potential targets in this pathway downstream of LPA." (PMID 28273928, 2017).
Insulin resistance (1 paper, 2017). Increased resistance towards insulin, that is, diminished effectiveness of insulin in reducing blood glucose levels. "PLPP1 deletion was not sufficient to protect from diet-induced insulin resistance compared to control mice." (PMID 28273928, 2017).
renal cell cancer (1 paper, 2023). "Conversely, elevated levels of PLPP2 have been observed in many cancers, including liver and prostate, breast and renal cell cancer, which was opposite to the expression pattern of PLPP1 and PLPP3." (PMID 37996944, 2023).
cancer (8 papers, 2020 to 2026). A tumor composed of atypical neoplastic, often pleomorphic cells that invade other tissues. "AKR1C1, CYP27A1, CYP2C9, GLB1, HMGCS2, and PLPP1, all six LMRGs, have been implicated in the genesis and progression of cancer." (PMID 36936948, 2023). "Considerable evidence has been accumulated about the functions of LPPs (PLPP1–3) in many physio-pathological processes, including cancer." (PMID 32887262, 2020). "Alterations (amplification, deletion, and mutation) of PLPP1–3 are not common in cancers." (PMID 32887262, 2020). "In vitro experiments had also shown that knockdown of PLPP2 weakened the growth of anchor-dependent cancer cell lines and reduced cell proliferation by delaying S-phase entry, unlike what was seen with PLPP1 and PLPP3." (PMID 37996944, 2023). "The function of PLPP1 related to cancer has not been reported." (PMID 38069368, 2023).
tumor (8 papers, 2017 to 2026). "T cell-specific deletion of Plpp1 impairs anti-tumor immunity and promotes T cell death caused by iron apoptosis." (PMID 39596288, 2024). "Lower levels of PLPP1 mRNA expression in tumor tissues than in surrounding normal tissues are linked to a worse prognosis." (PMID 36936948, 2023). "Using syngeneic and xenograft mouse models showed that PLPP1 overexpression in BC cells decreased tumor growth and the metastasis." (PMID 28122328, 2017). "It was discovered that the reduced levels of phosphatidylcholine (PC) and phosphatidylethanolamine (PE) in CD8+ T cells within the tumor were attributed to the diminished expression of phosphatidylphosphatase 1 (Plpp1), an enzyme that catalyzes the synthesis of PE and PC." (PMID 39596288, 2024). "PLPP1 degrades lysophosphatidate and is often down-regulated in tumor types." (PMID 28122328, 2017).
PLPP1 also shares sentences with these, for which no sentence is quoted: lung squamous cell carcinoma (2 papers); prostate carcinoma (2); alcoholic fatty liver disease (1); colon cancer (1); colorectal tumors (1); congenital heart defects (1); diffuse large B-cell lymphoma (1); fungal infection (1); infection (1); liver cancer (1); lymphoid neoplasm (1); Obesity (1); thymoma (1); toxoplasmosis (1).